EPO (erythropoietin)
Diseases named in the same sentence as EPO in open-access papers (continued):
Sharing a sentence is not in itself a finding about the gene and the disease.
Stroke (continued). "A systematic review and meta-analysis of EPO in experimental stroke highlighted a reduction of infarct volumes by 30% and an improvement of neurobehavioral outcomes by 40% in rodents after EPO administration following AIS." (PMID 35813499, 2022). "Next, we investigated the influence of stroke and EPO-administration on the activation of the inflammasomes NLRP3, NLRC4 and AIM2, and their downstreaming cascade." (PMID 34628598, 2022). "The mouse TfRMAb-EPO surrogate fusion protein was constructed to investigate the efficacy of the brain-penetrating EPO in an experimental model of stroke and PD." (PMID 35890374, 2022). "In a focal cerebral ischemia model in mice deficient for TGF-β-activated kinase 1 (TAK1) in microglia/macrophages, a study demonstrated that EPO administration improved clinical outcomes and dampened stroke-induced activation of TAK1 and inflammasome cascades." (PMID 35250554, 2022). "IGF-1 and EPO released from reactive astrocytes in the ischemic brain also enhance oligodendrogenesis after stroke." (PMID 35743941, 2022). "Neurotrophins were also developed as new treatments of acute stroke, and FGF-2 and EPO were administered as IV infusions within the first 5 h of the stroke." (PMID 35745855, 2022). "Taken together, our findings showed that EA at the GV26 acupoint can significantly attenuate ischemic injury after stroke and promote angiogenesis via activation of EPO-mediated Src and VEGF signaling pathways." (PMID 36108080, 2022). "EPO reduced the stroke-induced elevated protein levels of all three inflammasomes at both reperfusion timepoints (p < 0.05)." (PMID 34628598, 2022). "EPO administration improved clinical outcomes and dampened stroke-induced activation of TAK1 and inflammasome cascades, which was not evident after the deletion of Mi/MΦ TAK1." (PMID 34628598, 2022). "Both Tak1fl/fl (p < 0.05) and Cx3cr1creER-Tak1fl/fl mice (p < 0.01) gained clinical benefits from EPO administration over the entire observation period of 72 h after stroke." (PMID 34628598, 2022). "EPO has been clinically approved for the treatment of renal anemia for many years and has shown solid safety and efficacy after stroke in several preclinical studies, thus, it was also tested in stroke patients." (PMID 34628598, 2022). "Nevertheless, a subgroup analysis in this study revealed that EPO administration on its own was protective in stroke patients." (PMID 35813499, 2022). "The mouse TfRMAb-EPO fusion protein was neuroprotective in a reversible middle cerebral artery occlusion (MACO) stroke model, dosed at 1 mg/kg BW IV following MACO." (PMID 35890374, 2022). "We aimed to investigate the efficacy and safety of cranial MBH procedures under local anesthesia for augmenting transdural revascularization after EPO treatment in patients with stroke with perfusion impairments." (PMID 35579016, 2022). "Since no attempt was made to re-engineer the neurotrophin for BBB delivery, the trials met with the expected failed results for either the intravenous fibroblast growth factor (FGF)-2 stroke trial or the intravenous erythropoietin (EPO) stroke trial." (PMID 35745855, 2022). "In a proof of concept pilot study (phase I/II), EPO was found not only to be innocuous to stroke patients but also to significantly reduce stroke volumes within 8 h of the onset of clinical symptoms." (PMID 35813499, 2022). "In a clinical trial study with human patients with acute ischemic stroke, EPO was shown to significantly reduce infarct size and improve functional outcomes when it was administered eight hours after stroke onset." (PMID 33920974, 2021). "In that study, higher EPO levels were associated with a more favorable outcome, which would agree with the many preclinical studies on a protective effect of EPO in stroke." (PMID 32733466, 2020). "This did not only damage further work on EPO in stroke, but also influenced other EPO trials negatively." (PMID 32546125, 2020).
Stroke (continued). "The neuroprotection of intravenous EPO in stroke was examined, but this clinical trial failed, because (a) EPO does not cross the intact BBB, and (b) the BBB is intact in the early hours after stroke when neuroprotection is still possible." (PMID 33207605, 2020). "Erythropoietin (EPO) is a hematopoietic cytokine that shows neuroprotective effects in stroke by enhancing angiogenesis and neurogenesis and by upregulating synaptic plasticity-related genes, including BDNF." (PMID 32399020, 2020). "Depending on the study design, preclinical studies on EPO in stroke models indicate an improvement in infarct size by up to 32% and neurobehavioral outcomes by almost 40%." (PMID 33312715, 2020). "Some RCTs also suggested that EPO therapy significantly improved long-term neurological prognosis and reduce some adverse events in patients after stroke." (PMID 33178833, 2020). "Experimental research on rodent stroke models provides robust evidence for the antiedematic effects of EPO, which has particularly been attributed to a preserved barrier function of the BBB." (PMID 33312715, 2020). "The hydrogels encapsulating HGF or EPO also increased migration of neuroblasts into the stroke-injured region." (PMID 32411087, 2020). "Other mechanisms implicated in the pathogenesis of stroke may play a role in determining the risk of secondary events, including oxidative stress and the adaptive response to it and activation of neuroprotective pathways by hypoxia, for instance through induction of erythropoietin (EPO)." (PMID 32733466, 2020). "Owing to its enhanced transport across the BBB, an anti-TfR monoclonal antibody-EPO conjugate intravenously injected into mouse stroke models dramatically reduced the hemispheric stroke volume compared to its antibody-free counterpart." (PMID 31242683, 2019). "Hyaluronic acid is used as an injectable hydrogel, applied in order to gain a controlled transfer of erythropoietin (EPO) in the stroke treatment, which endorses neurogenesis and tissue repair." (PMID 31130624, 2019). "Lastly, the common signaling pathway of hUCBC and EPO treatment for stroke injury should be elucidated." (PMID 31024439, 2019). "This study contributes to future research on EPO‐related therapy in stroke and fibroblast‐assisted cell therapy in neurological diseases." (PMID 30920178, 2019). "Stroke promoted an increase of Chop mRNA in wildtype mice after 6 h of reperfusion and EPO significantly mitigated this effect (p = 0.0355)." (PMID 31683519, 2019). "The current study also demonstrated the therapeutic efficacy of delayed administration of EPO during the subacute stage of stroke, which is in accordance with previous research." (PMID 31024439, 2019). "Taken together, hUCBC and EPO appear to share the same signaling pathways in their therapeutic mechanisms for recovery after stroke." (PMID 31024439, 2019). "In this study, after we singly transplanted EPO‐producing fibroblasts into the infarcted striatum, a high EPO concentration was detected in the infarcted brain for at least 1 week, implying the secretion of EPO from fibroblasts at the early stage of stroke." (PMID 30920178, 2019). "Post-ischemic treatment with EPO, hUCBC, or hUCBC+EPO improved functional outcomes in a subacute stroke rat model." (PMID 31024439, 2019). "The EPO‐producing fibroblasts can thus secret BDNF and EPO simultaneously in the infarcted area, which enhanced the post‐stroke neurogenesis in a highly effective way." (PMID 30920178, 2019). "In conclusion, our results suggest that hUCBC infusion in combination with EPO administration demonstrates therapeutic efficacy in the treatment of stroke-induced injury by promoting neurogenesis and angiogenesis." (PMID 31024439, 2019). "Originally identified for its role in erythropoiesis, erythropoietin (EPO) was later shown to be neuroprotective in a variety of animal models of neurological conditions including stroke, TBI and multiple sclerosis (MS)." (PMID 30745876, 2019).
Stroke (continued). "In this regard, it was demonstrated that EPO can trigger a wide spectrum of protective effects, including improvement in learning and memory, promoting CNS development or blocking cell death in stroke models." (PMID 31379495, 2019). "Thirty adult male Wistar rats were randomly divided into 5 groups: sham, control and 3 pretreatment groups: single dose, double dose, and triple dose that received 1000 U/kg of erythropoietin before stroke induction in different times intraperitoneally." (PMID 30719249, 2018). "The use of EPO in the treatment of stroke requires high doses and multiple administrations, which can lead to a high haematocrit and an increase in the number of platelets, which increase the possibility of microcoagulation and secondary infarctions." (PMID 29438293, 2018). "There are abundant data indicated that EPO have neuroprotective activities after traumatic brain injury, stroke, and neurodegenerative diseases." (PMID 29385149, 2018). "Our research demonstrated that erythropoietin increased blood glucose levels in all groups, especially in the acute phase of stroke." (PMID 30719249, 2018). "The results of our study suggested that injecting a single dose of erythropoietin pretreatment (1000 U/kg) 30 minutes before the stroke induction, significantly reduced infarct volume damage and improved neurological deficits." (PMID 30719249, 2018). "This enhancement was significant in the double and triple dose erythropoietin pretreatment groups, compared to control and single dose groups; especially in the first and sixth hours after the stroke (P<0.05)." (PMID 30719249, 2018). "Here we found that GSK360A induced EPO production well above normal limits in plasma that persisted 24 hours after stroke." (PMID 28880966, 2017). "Delayed erythropoietin therapy (1000 U/kg per dose × three doses) improves histological and behavioral outcomes at one month following transient neonatal stroke induced by transient middle cerebral artery occlusion for 3 h in P10 Sprague-Dawley rats." (PMID 28134843, 2017). "Similar to VEGF, EPO is produced under hypoxic conditions, which can protect neurons from oxidative stress, ischemia, and stroke." (PMID 28197080, 2017). "Meanwhile, EPO increases oligodendrogenesis and decreases gliosis to contribute to white matter repair 14 days after stroke in adult mice." (PMID 28840056, 2017). "The first clinical evidence of the utility of rHu-EPO in the treatment of stroke was obtained in the early 2000s." (PMID 28676085, 2017). "Erythropoietin has emerged as a promising candidate for neuroprotection in animal models of ischemia and in stroke patients for years." (PMID 28840056, 2017). "In this study, we examined the potential of a novel EPO-based short peptide, MK-X, as a novel drug for stroke treatment in comparison with EPO." (PMID 28817120, 2017). "Here, kidney EPO mRNA expression was also observed to increase much earlier (i.e., 5 hours after tMCAO stroke)." (PMID 28880966, 2017). "In the kidney, GSK360A dramatically increased EPO mRNA early post-stroke as compared to vehicle (e.g., group by time interaction factor was significant; p<0.05)." (PMID 28880966, 2017). "The GSK360-induced increase in EPO was higher 24 hour post-stroke suggesting a more prolonged increase then that observed without stroke." (PMID 28880966, 2017). "Although combined administration of EPO and G-CSF represents a promising therapeutic strategy for stroke patients, most studies have focused on peripheral efficacy for the treatment of myelodysplastic syndromes." (PMID 27043535, 2016). "In conclusion, this exploratory study suggests a novel strategy of EPO+G-CSF combination therapy for stroke patients." (PMID 27043535, 2016). "Although many studies of promising hematopoietic neuroprotectants have been undertaken for stroke treatment, most trials have focused on acute or subacute stroke treatment with a single administration of either EPO or G-CSF." (PMID 27043535, 2016).
Stroke (continued). "Previous studies tried to demonstrate the safety and potential beneficial effects of a single pharmacological treatment using either EPO or G-CSF for chronic multiple sclerosis and stroke." (PMID 27043535, 2016). "Multivariate analysis showed that a history of previous stroke was a significant independent predictor of long-term severe neurological deficit, whereas EPO therapy was significantly and independently predictive of freedom from severe neurological deficit." (PMID 25888250, 2015). "Subjects received EPO doses at 6, 24, and 48 h after the onset of stroke symptoms, and had increased mortality (16.4%) compared to placebo (9.0%) and increased hemorrhagic complications." (PMID 25942688, 2015). "In adults, EPO administered daily for three days immediately following stroke reduced infarct size, improved recovery of cognitive function, and decreased neurological deficits in the short-term." (PMID 25942688, 2015). "For example, three doses of EPO given over one week, with the first dose given immediately after stroke, result in improved brain volume and cognitive function." (PMID 25942688, 2015). "In this study, it was noted that treatment was most effective when the first EPO dose was received within 8 h of stroke." (PMID 25942688, 2015). "EPO-TAT administered at the onset of post-stroke reperfusion showed the ability across the BBB for neuroprotection." (PMID 24587228, 2014). "Systemic administration of EPO after induction of focal cerebral ischemia has been demonstrated to exert a potential neuroprotective effect on the outcome of stroke; however, there is a limited therapeutic time window." (PMID 24587228, 2014). "This said, several studies have been conducted concerning the safety and efficacy of EPO administered shortly after stroke." (PMID 23675319, 2013). "In models of stroke, spinal cord injury, traumatic brain injury, brain edema, EPO is clearly neuroprotective." (PMID 23497299, 2013). "This strongly suggests that EPO enhances plasticity when administered in the subacute phase after stroke." (PMID 23497299, 2013). "Administration of recombinant human EPO (rhEPO) 24 h after stroke induced sustained OPC proliferation in the peri-infarct white matter and the SVZ." (PMID 24194700, 2013). "EPO decreases inflammatory mediators, and thus has been suggested for various clinical indications such as stroke, multiple sclerosis (MS), schizophrenia, retinopathy, Parkinson’s disease, epilepsy, brain trauma and spinal cord injury." (PMID 23493953, 2012). "Based on results of extensive animal experimental stroke studies erythropoietin (EPO) and the granulocyte-colony-stimulating factor (G-CSF) were thought to be particularly promising for further clinical development." (PMID 23109881, 2012). "Beyond their neuroprotective properties, G-CSF and EPO improve post-stroke regeneration by enhancing neurogenesis and angiogenesis." (PMID 23109881, 2012). "It has also been shown that rHu-EPO and its derivatives stimulate the process of angiogenesis and neurogenesis, providing a favorable microenvironment for neural plasticity during stroke recovery." (PMID 22701364, 2012). "EPO can protect neurons from oxidative stress, spinal cord ischemia, retinal disease, stroke, and demyelinating disease." (PMID 23109841, 2012). "The large number of animal stroke studies on EPO and G-CSF enabled preclinical meta-analyses which convincingly demonstrated that both factors reduce infarct volumes and improve functional outcomes." (PMID 23109881, 2012). "EPO treatment stimulates oligodendrocyte progenitor cells and improves the functional outcome after experimental stroke and experimental autoimmune encephalitis." (PMID 22741599, 2012). "Clinical studies of erythropoietin treatment in stroke and other diseases provide insight on safety and potential adverse effects and underscore the potential pleiotropic activity of erythropoietin." (PMID 22567318, 2012).
Stroke (continued). "The multiple mechanisms by which EPO is active, as well as the successful phase II trial in human stroke, suggest that the use of rhEPO will likely translate successfully into human trials." (PMID 21766022, 2011). "In a transgenic mouse model overexpressing human EPO, the authors demonstrated that these mice fail to develop hypertension, stroke, myocardial infarction, or thromboembolism but do have hematocrit levels of approximately 80% with generalized vasodilatation." (PMID 21943500, 2011). "The potent neuroprotection property of the HIRMAb-EPO fusion protein was investigated in a rat stroke model, the permanent middle cerebral artery occlusion (MCAO) model." (PMID 21766022, 2011). "Systemic administration of EPO has been found to be active in a large number of animal models associated with IRI, including stroke, myocardial infarction, acute kidney injury, hemorrhagic shock, and SIRS." (PMID 21943500, 2011). "This also encourages the thesis that EPO can be directly used for treatment of stroke or neurodegenerative diseases as we provide evidence for a direct effect of EPO on neuronal cells." (PMID 21126346, 2010). "Erythropoietin was shown to have neuronal protective effects in animal models of ischemia-induced stroke and brain injury." (PMID 20950484, 2010). "Overall, the potential side effects of EPO will presumably prevent the conduction of further clinical stroke trials." (PMID 20459870, 2010). "The recently published double-blind, placebo-controlled, randomized phase II/III German Multicenter EPO Stroke Trial was conducted to evaluate the efficacy and safety of Erythropoietin (EPO) in stroke patients." (PMID 20459870, 2010). "In conclusion, the intranasal application of Neuro-EPO has a better neuroprotective effect than intraperitoneal EPO, evidenced by the significant improvement of neurological, cognitive, and histological status in the animal model of stroke employed." (PMID 21103798, 2010). "Erythropoietin (EPO), a hematopoietic cytokine, enhances neurogenesis and angiogenesis during stroke recovery." (PMID 20552017, 2010). "In a rat model of neonatal stroke, EPO reduced the infarct volume and improved long-term behavioral outcome more significantly in females than in males." (PMID 21629441, 2010). "More importantly, our in vivo and in vitro data indicate that exogenous EPO substantially amplifies stroke-induced oligodendrogenesis from both sources." (PMID 20552017, 2010). "Similar to EPO, G-CSF has also shown neuroprotective potential in animal models of stroke and in neuronal cultures." (PMID 20404921, 2010). "Recombinant human EPO (rhEPO) at a dose of 5,000 U/kg (n = 18) or saline (n = 18) was intraperitoneally administered daily for 7 days starting 24 h after stroke onset." (PMID 20552017, 2010). "In the current study, we investigated the effect of EPO on oliogdendrogenesis in a rat model of embolic stroke." (PMID 20552017, 2010). "A new opportunity was opened when the beneficial effect of neuro-protective drugs, including erythropoietin (epoietin-beta, Epo), was demonstrated both in animals and humans during stroke." (PMID 19630971, 2009). "Intranasal insulin-like growth factor-I, deferoxamine, and erythropoietin have been shown to protect the brain against stroke in animal models." (PMID 19091002, 2008). "Assuming that parenchymal destruction affects both EPO and hS3 mRNA counts equally, the EPO to hS3 ratio may provide a more reliable representation of EPO and hS3 mRNA expression dynamics after stroke." (PMID 41602576, 2026). "There is one descriptive study which provides evidence that EPO and EPOR are upregulated in human hypoxic brains lacking quantitative validation, and one study in humans demonstrating serum EPO levels positively correlate with stroke severity and EPO increase with improved functional outcome." (PMID 41602576, 2026).